TMEM97 (transmembrane protein 97)
Diseases named in the same sentence as TMEM97 in open-access papers (continued):
Sharing a sentence is not in itself a finding about the gene and the disease.
cancer (continued). "Understanding molecular functions of TMEM97 in proliferation and cholesterol metabolism will be important to develop strategies to diagnose and treat cancer and cholesterol disorders using a rich collection of TMEM97 radiotracers and ligands." (PMID 32668577, 2020). "It is known that overexpression of TMEM97 is positively correlated with tumor proliferation, metastasis, and reduced survival in various cancer types." (PMID 32456310, 2020). "TMEM97 expression in normal and cancer tissues has been studied using an σ2R binding assay and immunohistochemistry to measure protein levels and using northern-blot, quantitative RT-PCR, DNA microarray or RNAseq methods to determine mRNA levels." (PMID 32668577, 2020). "Numerous studies demonstrated that TMEM97 was ubiquitously expressed in a wide variety of normal human tissues and cancer." (PMID 32668577, 2020). "Sigma-2 receptors, lately identified as TMEM97 proteins, are overexpressed in diverse types of cancers and their modulation leads to cell death upon the activation of a number of still investigated pathways." (PMID 32397184, 2020). "The overexpression of σ2R/TMEM97 has previously been reported in certain cells isolated from different cancer types." (PMID 31973006, 2020). "TMEM97 is also involved in cancer: its agonist, PB221, significantly inhibited the migration and invasion of ALTS1C1 cells (a murine brain tumor cell line)." (PMID 33233619, 2020). "Considering the apparent context-dependent actions of Sigma2/TMEM97, it will be of interest to further evaluate this approach in a broader range of cancer cell lines." (PMID 31695608, 2019). "In this model, the high expression level of TMEM97 has been correlated with the resistance of cancer to platinum-based treatment but also with poor patient survival." (PMID 30574087, 2018). "Elevated expression of TMEM97 or MAC30 has been linked with poor clinical parameters in gastric, colorectal, breast, and ovarian cancers, but the biological mechanism involved remains unknown." (PMID 38067394, 2023). "Overall, we here provide novel data regarding expression—especially of PGRMC1 and σ2/TMEM97, for which very little is known —in different human cancer types and cell lines included in a significant tool for anticancer drug development, the NCI60 cell line panel." (PMID 33466391, 2021). "However, σ1, PGRMC1, and σ2/TMEM97 were generally expressed differentially, even between cell lines of the same cancer type." (PMID 33466391, 2021). "Further in cells with overexpression of TMEM97, more death of cancer cells can be induced by NO1." (PMID 33233619, 2020). "Taken together, TMEM97 is regulated by oncogenic factors in certain cancer cells and may be related to cancer development and proliferation in certain tumors." (PMID 32668577, 2020). "Limited research examined the regulation of TMEM97 expression in cancer." (PMID 32668577, 2020). "TMEM97 is expressed in many cell types and play important functions in neurons and cancer cells." (PMID 33233619, 2020). "Given the metabolic dependency of cancer cells on cholesterol and various effects of cholesterol metabolites on cancer, TMEM97 may play roles in cancer via involvement in cholesterol homeostasis." (PMID 32668577, 2020). "There are relatively few publications specifically regarding TMEM97 in cancer." (PMID 31695608, 2019). "Furthermore, more data are needed to clarify the roles of TMEM97 alone and in relation to Sigma1 in cancer pharmacology." (PMID 31695608, 2019). "Several prototypic Sigma1 and Sigma2/TMEM97 compounds are reported to influence cancer cell survival, proliferation, growth, adhesion, motility, and protein homeostasis pathways, thereby suggesting a potentially broad range of therapeutic opportunities for targeting these proteins." (PMID 31695608, 2019).
cancer (continued). "Prior to the identification of the sigma-2 receptor as TMEM97, the function of the sigma-2 receptor was studied through high affinity ligands and appeared to be linked to neurodegenerative diseases and cancer development." (PMID 31109310, 2019). "Furthermore, TMEM97 appears to play the role of tumor suppressor or promotes tumor growth, depending upon the cancer type." (PMID 31695608, 2019). "The differential expression of TMEM97 in cancer cells suggest that this protein may have a role in tumor development, growth, and proliferation." (PMID 30701090, 2019). "TMEM97, which is overexpressed in this type of cancer, is a target of miR-152-3p." (PMID 30574087, 2018). "This unexpected prediction of enzymatic functions for TM6SF and MAC30/TMEM97 is important because it now permits detailed experiments to investigate the function of these key proteins in various human pathologies, from cardiovascular disease to cancer." (PMID 25566323, 2014). "Thus, these compounds may also be valuable medicinal chemistry starting materials for the modulation of sigma 2/TMEM97 outside of cancer, including in neurodegeneration and pain." (PMID 39942783, 2025). "As a result, a diverse set of σ2R/TMEM97 radiotracers and ligands has been developed for use in strategies targeting cancer diagnosis and treatment." (PMID 39804138, 2025). "Sigma intracellular receptor 2 (TMEM97) is a transmembrane protein involved in cholesterol homeostasis, cancer development, and neurological functions." (PMID 41462954, 2025). "Because barbamide and its parent fraction showed affinity for the sigma-1 receptor and the sigma-2 receptor (aka TMEM97) both known to be up-regulated in some TNBC and other cancer cell lines, we wanted to investigate its cytotoxic effects on these cells." (PMID 36827151, 2023). "The sigma-2 receptor/transmembrane protein 97 (σ2R/TMRM97) is a promising biomarker of tumor proliferation and a target for cancer therapy." (PMID 36559015, 2022). "The high expression of σ2R/TMEM97 in proliferating cancer cells makes it a biomarker and target for cancer diagnosis and therapy." (PMID 36456686, 2022). "In the past decade, σ2R/TMEM97 has been identified as a potential target for the imaging and treatment of cancer." (PMID 36559015, 2022). "Regarding cancer stage and N-stage, there were significant correlations for TMEM206, TMEM97 (p = 0.0479, p = 0.0075), and TMEM45B (p = 0.0011), respectively." (PMID 34638224, 2021). "The 3D structure of TMEM97/S2R, once understood, could shed fundamental light on its biological functions and their potential involvement in a broad spectrum of driver pathways of cancer and neurodegenerative diseases, thus facilitating the development of novel effective drugs." (PMID 30042674, 2018). "σ2R/TMEM97 modulation decreases SOCE and increases apoptosis of cancer cells." (PMID 41008535, 2025). "Our group previously reported that the σ2R/TMEM97 is a good biomarker for measuring the proliferative status of cancer cells, which is defined as the ratio of the density of receptors in proliferating (P) versus quiescent (Q) cancer cells." (PMID 36559015, 2022). "TMEM97, which is transcriptionally controlled by SREBF2, is an intracellular orphan receptor that binds numerous drugs and highly expressed in various proliferating cancer cells involving cell survival, morphology, and differentiation." (PMID 34349727, 2021). "TMEM97 has been validated as a biomarker of proliferative status and the radioligand of TMEM97, [18F]ISO-1, has been developed and validated as a PET imaging biomarker of proliferative status of tumors and as a predictor of the cancer therapy response." (PMID 32668577, 2020).
cancer (continued). "Interestingly, the decrease in TMEM97 expression exerted by BS148 was similar to that observed for S2R RNA interference-mediated knockdown, which has been already shown to inhibit both proliferation and migration of cancer cells." (PMID 37298633, 2023). "Although there is currently no clinically used anti-cancer drug that targets Sigma1 or Sigma2/TMEM97, a growing body of evidence supports the potential of small-molecule compounds with affinity for these proteins, putative sigma ligands, as therapeutic agents to treat cancer." (PMID 31695608, 2019). "Furthermore, as reported in other tumors types, upregulation of DAB2, RND3, TMEM97, CSE1L, MYO1C, and PTPRK have been shown to suppress or functionally redistribute E-cadherin expression in cancer cells, resulting in EMT, increased invasion, advanced tumor stage and poor patient survival." (PMID 27863424, 2016).
tumor (67 papers, 2005 to 2025). "In 2017, the transmembrane protein 97 (TMEM97), which is also known as meningioma-associated protein 30 (MAC30), was identified as a gene coding for S2R activity in tumor cell lines." (PMID 37047353, 2023). "After implantation for 28 days, tumor growth was significantly suppressed in the TMEM97-deficient cell group." (PMID 34615853, 2021). "Immunohistochemical staining revealed that tumor tissues from TMEM97-deficient group displayed decreased expression of active and total β-catenin." (PMID 34615853, 2021). "TMEM97 overexpression was associated with poor tumor differentiation and shorter overall patient survival." (PMID 30574087, 2018). "In addition, each protein in the complex has higher expression in high-grade tumors, and all three are positively associated with tumor cell proliferation rates, with the strongest association seen with TMEM97." (PMID 39804138, 2025). "TMEM97 silencing suppresses tumor proliferation, arrests the cell cycle, inhibits cell invasion, and decreases the migration of GBM cells." (PMID 38167429, 2024). "TMEM97 mRNA levels are significantly increased in tumor vs. healthy tissues, supporting the rationale of TMEM97-targeting drugs." (PMID 37298633, 2023). "To illuminate the difference observed between the two tumor cell lines, we performed Western blot experiments of whole cell lysates to evaluate the expression levels of TMEM97 and PGRMC1." (PMID 37047353, 2023). "Tumor cells with TMEM97 knockdown were more sensitive to OH-tamoxifen than the vector control cells." (PMID 38067394, 2023). "The expression level of TMEM97 was higher in tumor tissue compared to normal tissues of NSCLC patients." (PMID 37367036, 2023). "In PCa, miR-152-3p serves as a tumor repressor to suppress TMEM97 expression, thus hindering tumor growth." (PMID 35123415, 2022). "As revealed by the sphere formation assay, knockout of TMEM97 markedly decreased the number and size of tumor spheres in Hs578T and MDA-MB-231 cells." (PMID 34615853, 2021). "Knockout of TMEM97 resulted in an obvious reduction in the volume and weight of tumor xenografts compared with the control group." (PMID 34615853, 2021). "Sigma‐2 receptor/TMEM97 is overexpressed in many tumours, and sigma‐2 receptor ligands are under investigation for cancer therapy." (PMID 34783163, 2021). "Histological analysis of tumor samples showed that tumor cell density and Ki67 expression were decreased in tumor tissues from TMEM97 knockout group." (PMID 34615853, 2021). "Studies of this complex accelerated with the identification of TMEM97 as a gene coding for S2R activity in tumor cell lines in 2017." (PMID 33028631, 2020). "It is reported that TMEM97 is upregulated in some tumors but downregulated in other tumors and it is required for cell proliferation in certain tumor cells." (PMID 32668577, 2020). "Over the past two decades, a number of publications have suggested a potential role for Sigma1 and Sigma2/TMEM97 in tumor biology." (PMID 31695608, 2019). "Much of our knowledge regarding Sigma1 and Sigma2/TMEM97 in tumor biology is derived from studies with synthetic compounds." (PMID 31695608, 2019). "Overexpression of TMEM97 was positively correlated with tumor stage, metastasis, and shorter survival time of patients with various cancers." (PMID 30701090, 2019). "One study on ovarian cancer showed that high expression of TMEM97 was correlated with high histological grade and tumor recurrence." (PMID 30574087, 2018). "In an oncogenic context, s2R/TMEM97 is implicated in the Wnt/beta-catenin pathway and upregulates low-density lipoprotein receptor related protein 6 (LRP6) phosphorylation that ultimately results in tumor growth." (PMID 38866499, 2024). "Moreover, TMEM97 protein level was correlated with poor tumor differentiation and a shorter survival in patients with NSCLC." (PMID 37367036, 2023). "Interestingly, TMEM97 is overexpressed in proliferating tumours and believed to be involved in cholesterol homeostasis." (PMID 37132223, 2023).
tumor (continued). "The expression of TMEM17, TMEM97, TMEM140, TMEM156, TMEM173, and TMEM206 show significant correlation with immune, stromal, and ESTIMATE scores which indicates a strong association between those TMEMs and immune response inside a tumor microenvironment." (PMID 34638224, 2021). "TMEM97 has been proposed as a potential tumor suppressor in pancreas and prostate cancer." (PMID 31695608, 2019). "Indeed, the expression of TMEM97 has been analyzed in 20 cases of NSCLC compared to adjacent healthy tissue: 65% of patients showed a higher expression level of TMEM97 in tumor tissue compared to healthy tissue." (PMID 30574087, 2018). "TMEM97 may be required for cell proliferation in certain tumor cells." (PMID 32668577, 2020). "In addition, the S2R/TMEM97 may exert antiproliferative effects in actively proliferating tumor cells, attenuating ER stress." (PMID 30042674, 2018). "Moreover, the putative overlapping of the pharmacological activity and ligand binding profile of S2R with TMEM97, a protein overexpressed in some tumor types, reinforces the idea that this SR subtype could be a marker for tumorigenesis." (PMID 30042674, 2018). "Some of TMEM proteins act as tumor suppressors such as TMEM7, TMEM25, TMEM97, and TMEM176A; while a large number of them act as oncogenes such as TMEM14A and TMEM158." (PMID 37335919, 2023). "Cluster I consisted of genes upregulated in CC cells, which included tumor-related genes such as LGR4, AGR2, PCAF, TMEM97, FRAT2, EFNB2 and ZIC2." (PMID 21333016, 2011). "TMEM expression was also dependent on tumor invasion to space surrounding a nerve for ANO1, TMEM116, and TMEM97 (p = 0.002, p < 0.0001, p = 0.008) and on angiolymphatic invasion for TMEM48, RTP3, TMEM173, and TMEM116 (p < 0.0001, p = 0.0267, p = 0.001, p = 0.0053, respectively)." (PMID 34638224, 2021). "A similar study performed in human SQCLC showed TMEM97 overexpression in 26 of the 32 tumor samples in comparison to corresponding non-tumor tissues." (PMID 30574087, 2018). "TMEM97 is regulated by upstream oncogenic signals such as EGF, TGF-β and microRNA in some but not other tumor cells." (PMID 32668577, 2020).
neurodegenerative disease (11 papers, 2017 to 2025). A disorder of the central nervous system characterized by gradual and progressive loss of neural tissue and neurologic function. "This work also provides persuasive experimental support for a new therapeutic strategy to protect RGCs and other neurons in neurodegenerative diseases by inhibiting σ2R/TMEM97." (PMID 36456686, 2022). "The role of σ2R/TMEM97 in neurodegenerative diseases has been explored in the brain and the retina." (PMID 41008535, 2025). "This information will provide potential insights into the diverse role of σ2R/TMEM97 in different cell types and diseases, facilitating the development of new drug treatments in AMD and neurodegenerative diseases." (PMID 41008535, 2025). "In addition, multiple lines of evidence from genetic studies, cell studies, animal studies, and clinical trials strongly suggest a role of σ2R/TMEM97 in AMD and neurodegenerative diseases of the CNS." (PMID 41008535, 2025). "This study opens a new avenue for studying the role of σ2R/TMEM97 as an epigenetic regulator of genes involved in cell pathophysiology, such as oxidative stress and pro-inflammatory cascades, related to AMD and other neurodegenerative diseases." (PMID 41008535, 2025).
neurological disorders (9 papers, 2020 to 2025). "These evidences indicate that the sigma-2 receptor/TMEM97 may be a promising target for the treatment of neurological diseases." (PMID 33233619, 2020).
TMEM97 also shares sentences with these, for which no sentence is quoted: schizophrenia (5 papers); infection (3); breast adenocarcinoma (2); dementia (2); dementia with Lewy bodies (2); metabolic disease (2); adenoma (1); age-related macular degeneration (1); anxiety disorder (1); astrocytoma (1); brain injury (1); brain tumors (1); cardiovascular disease (1); cognitive decline (1); colon cancer (1); COVID-19 (1); diabetic retinopathy (1); dry age related macular degeneration (1); Dystonia (1); glioblastoma (1); Insulin resistance (1); kidney cancer (1); lung adenocarcinoma (1); lymph node metastasis (1); lymphoma (1); malakoplakia (1); neuropathic pain (1); oral cancer (1); oral squamous cell carcinoma (1); pheochromocytoma (1).
A further 4 diseases each share a sentence with TMEM97 in 1 paper.